RNU6-600P (RNA, U6 small nuclear 600, pseudogene)
Gene: Small nuclear RNA gene on chromosome 12 (48,892,130 to 48,892,228, reverse strand). Ensembl gene ENSG00000199394.
Homologues: Orthologues: chimpanzee U6 (98% identical), macaque U6 (94% identical), mouse Gm23035 (68% identical), dog U6 (65% identical). Paralogues in human: RNU6-15P (85% identical), RNU6-820P (85% identical), RNU6-1130P (84% identical), RNU6-25P (84% identical), RNU6-41P (84% identical), RNU6-44P (84% identical), RNU6-7 (84% identical), RNU6-8 (84% identical), RNU6-1 (83% identical), RNU6-1127P (83% identical), RNU6-166P (83% identical), RNU6-16P (83% identical), and 1286 more.